RB1 (RB transcriptional corepressor 1)
Diseases named in the same sentence as RB1 in open-access papers (continued):
Sharing a sentence is not in itself a finding about the gene and the disease.
brain tumors (21 papers, 2003 to 2025). "In case of rs121913300 RB1 polymorphism, ∼20.48-fold increased risk of brain tumor was associated with homozygous mutant genotype (OR, 20.48; 95% CI, 2.72–154.21; P=0.003) in tumor patients." (PMID 32373934, 2020). "Zebrafish rb1 brain tumors caused by TALEN or CRISPR targeting are histologically similar to human central nervous system primitive neuroectodermal tumors (CNS-PNETs)." (PMID 29914980, 2018). "The majority of mutant rb1 alleles in somatic, germline and brain tumor tissues were frameshift mutations." (PMID 26345384, 2015). "Predisposing zebrafish to brain tumors by somatic inactivation of rb1 with site-specific nucleases will be useful for investigating pathways cooperating in brain tumorigenesis." (PMID 26345384, 2015). "The ANT relationship of IDH1 and RB1 mutations in brain tumors may have arisen due to the mutation preference of low- and high-grade gliomas that are respectively enriched with IDH1 mutations and mutations in Rb pathways including RB1 mutations." (PMID 39160568, 2024). "RB1 gene is found to be mutated in many cancers including brain tumor." (PMID 32373934, 2020). "For RB1 SNP rs137853294, dominant (OR, 1.62; 95% CI, 1.13–2.33; P=0.008) and additive genetic model (OR, 1.50; 95% CI, 1.11–2.01; P=0.007) showed significant association with increased risk of brain tumor." (PMID 32373934, 2020). "Our study provides new insight into the epigenetic processes that might drive pathogenesis in RB1 brain tumors, and identifies Rbbp4 and its associated chromatin remodeling complexes as potential target pathways to induce apoptosis in RB1 mutant brain cancer cells." (PMID 29914980, 2018). "The same group later used this rb1 mutant CNS-PNET model to understand the epigenetic regulators driving oncogenesis in this zebrafish brain tumour model." (PMID 36077320, 2022). "Rb1 is a tumor suppressor protein that exerts its function by regulating cell proliferation, and genetically rb1-mosaic adult zebrafish develop brain tumors." (PMID 34211495, 2021). "The present study was designed to determine the association between the genetic polymorphisms/expression variations of RB1 and CCND1 genes and brain tumor risk." (PMID 32373934, 2020). "Significant down-regulation of RB1 expression was observed in brain tumor patients when compared with adjacent controls, after qPCR and IHC." (PMID 32373934, 2020). "The results showed homozygous mutant genotype of RB1 gene polymorphism, rs121913300 (P=0.003) and CCND1 gene polymorphism rs614367 (P=0.01) were associated significantly with brain tumor risk." (PMID 32373934, 2020). "Present study examined the two exonic SNPs of RB1 gene (rs137853294 and rs121913300) in brain tumor patients." (PMID 32373934, 2020). "The present study encompasses the genetic analysis of RB1 exonic and CCND1 intergenic polymorphisms in brain tumor patients to find their association with brain carcinogenesis." (PMID 32373934, 2020). "In study cohort I, 250 brain tumor patients and 250 control individuals were examined for four selected SNPs including rs137853294, rs121913300 (RB1), rs614367 and rs498136 (CCND1)." (PMID 32373934, 2020). "Significant decreased mRNA level of RB1 gene was also observed in grade IV (P=0.004) brain tumor as compared with other grades." (PMID 32373934, 2020).
brain tumors (continued). "The present study was designed to explore the correlation between the genetic polymorphism of RB1 and CCND1 genes to brain tumor risk in Pakistani population." (PMID 32373934, 2020). "RB1 expression has observed significantly lower in brain tumour (P=0.005) than in normal tissue samples." (PMID 32373934, 2020). "In study cohort II, 96 brain tumor tissues and 96 healthy tissues were analyzed for the expression variation of RB1 and CCND1 genes." (PMID 32373934, 2020). "To gain insight into the molecular differences between rb1/rb1 mutant and rb1-transformed cells, we performed additional comparative analyses between the zebrafish rb1 mutant and brain tumor transcriptomes." (PMID 29914980, 2018). "The zebrafish rb1 brain tumors showed a similar pattern of differential gene expression across the 60 up- and 60 downregulated genes." (PMID 29914980, 2018). "We previously demonstrated that genome editing nucleases can be used to model brain tumors in zebrafish by targeted somatic inactivation of the rb1 tumor suppressor gene." (PMID 29914980, 2018). "We previously developed a zebrafish rb1 brain tumor model that resembles poorly differentiated primitive neuroectodermal tumors by somatic targeting of zebrafish rb1 with TALENs." (PMID 29914980, 2018). "Our zebrafish rb1 brain tumor model histologically and molecularly resembles human CNS-PNET, an embryonal tumor composed of proliferative neuroblast cells." (PMID 29914980, 2018). "Our analyses provide new insight into the genomic processes that drive oncogenesis in RB1 mutant brain tumors." (PMID 29914980, 2018). "Comparative transcriptome analysis of zebrafish rb1 brain tumors with rb1/rb1 homozygous mutant tissue suggests elevated expression of oligoneural precursor transcription factors, and chromatin remodelers distinguish neoplastic from mutant tissue." (PMID 29914980, 2018). "Together, these results demonstrate the zebrafish rb1 brain tumors have a highly proliferative, poorly differentiated state with an oligoneural precursor molecular signature found in human OLIG2+/SOX10+ and zebrafish NRAS CNS-PNETs." (PMID 29914980, 2018). "Examining the contribution of HDAC1 and RBBP4 to maintaining the progenitor-like state of RB1 brain tumors would shed light on the mechanism of chromatin remodeling in epigenetic control of tumor suppression." (PMID 29914980, 2018). "In this study, we used comparative genomics and developmental genetics to identify epigenetic regulators driving oncogenesis in a zebrafish retinoblastoma 1 (rb1) somatic-targeting model of RB1 mutant embryonal brain tumors." (PMID 29914980, 2018). "Transcription activator-like effector nuclease (TALEN) targeting of zebrafish rb1 leads to brain tumors with histological similarity to central nervous system primitive neuroectodermal tumors (CNS-PNETs)." (PMID 29914980, 2018). "We next compared the zebrafish rb1 brain tumor transcriptome to other zebrafish brain tumor models and to human CNS-PNET." (PMID 29914980, 2018). "Targeted inactivation of rb1 resulted in the early onset of brain tumors in zebrafish with significantly increased frequency of tumor incidence." (PMID 28903419, 2017). "Using RNA sequencing analysis in addition to histopathological and immunohistochemistry, we showed that brain tumors induced by rb1 somatic inactivation have molecular features of medulloblastoma-like PNETs." (PMID 28903419, 2017). "Using RNA sequencing analysis together with histopathology and immunohistochemistry, we have demonstrated that brain tumors induced by rb1 somatic inactivation have a molecular feature of MB-like primitive neuroectodermal tumors (PNETs)." (PMID 28903419, 2017). "In this study, brain tumors induced by somatic inactivation of rb1 showed incidence mainly in the cerebellum." (PMID 28903419, 2017).
brain tumors (continued). "Injection of rb1-TALEN mRNA also led to the formation of brain tumors at high frequency (58%, 31 weeks of age) in F0 tp53e7/e7 mutant zebrafish." (PMID 28903419, 2017). "Similar to cdkn2a/b inactivation of F0 tp53e7/e7 mutants, TALEN-mediated somatic inactivation of rb1 led to early onset of brain tumors in adult zebrafish." (PMID 28903419, 2017). "For these reasons, we assumed that brain tumors induced by somatic inactivation of rb1 are medulloblastoma like PNETs, which molecular comparative analysis of RNA-seq results confirmed." (PMID 28903419, 2017). "ZNF329 and RB1 significantly regulate those ‘mesenchymal’ gene expression signature genes for brain tumors." (PMID 27556418, 2016). "The brain neoplasm, however, was also heavily enriched for rb1 frameshift deletion (89%; Δ52 and Δ7) and rbl1 insertion (97%; +32)." (PMID 27739525, 2016). "For another real expression data from the patients affected by human brain tumors, CBDN predicts two potential important regulators ZNF329 and RB1 whose function are associated with brain tumors." (PMID 27556418, 2016). "To determine the mechanisms participating in an inactivation of the RB1 gene in malignant brain tumours, we investigated the methylation status at the CpG island within the promoter region of the RB1 gene." (PMID 12556968, 2003). "However, till now, no study has been reported to screen out the hotspot polymorphisms of RB1 and CCND1 genes along with expression variations of respective genes in brain tumor and different subtypes of brain tumor." (PMID 32373934, 2020). "In conclusion, it is suggested that polymorphisms/expression variations of RB1 and CCND1 genes may be associated with increased risk of brain tumor." (PMID 32373934, 2020). "The disruption of RB1-dependent transcriptional mechanisms controlling neural precursor quiescence and differentiation could be a part of oncogenesis in RB1 mutant brain tumors." (PMID 29914980, 2018). "A similar epigenetic mechanism in which Hdac1 and Rbbp4 associate with oligoneural precursor transcription factors might drive zebrafish rb1 brain tumor oncogenesis." (PMID 29914980, 2018). "The results were remarkably similar to the rb1 brain tumor transcriptome, suggesting that the activation of molecular pathways driving cell proliferation is controlled by similar mechanisms in rb1/rb1 mutant and rb1-transformed cells." (PMID 29914980, 2018). "Similar roles in neural progenitor proliferation and survival could drive unregulated tumor growth in zebrafish rb1 brain tumors." (PMID 29914980, 2018). "Also, TALEN-mediated rb1 somatic inactivation led to the development of brain tumors in the zebrafish model." (PMID 28903419, 2017). "Present study was designed to find out whether the polymorphisms or expressional variation in the RB1 and CCND1 genes can modify the risk for brain tumor, and if the effects of these polymorphisms differ in different pathological parameters of brain tumor patients." (PMID 32373934, 2020). "In this study, we compared the transcriptome of somatically engineered zebrafish rb1 primitive neuroectodermal-like brain tumors with homozygous rb1/rb1 mutants and identified epigenetic regulators that could contribute to the mechanism of RB1 mutant tumor oncogenesis." (PMID 29914980, 2018). "RB1 and CCND1 mRNA levels were observed in study cohort II including 96 brain tumor tissues and adjacent uninvolved healthy section used as control." (PMID 32373934, 2020). "Expression level of RB1, CCND1 and Ki-67 was also observed in 96 brain tumor section and adjacent control section using IHC." (PMID 32373934, 2020). "Expression levels of RB1 and CCND1 gene was also measured in cohort II of brain tumor patients and controls using qPCR and immunohistochemistry." (PMID 32373934, 2020). "Correlations were tested between RB1, CCND1 and Ki-67, clinical and pathological features of brain tumor patients group II." (PMID 32373934, 2020).
brain tumors (continued). "A significant negative correlation was observed between CCND1 vs RB1 (r = −0.54***, P<0.0001) and RB1 vs Ki-67 (r = −0.29*, P<0.05) in brain tumor patients." (PMID 32373934, 2020). "Spearman correlation showed significant negative correlation between RB1 vs proliferation marker, Ki-67 (r = −0.291*, P<0.05) in brain tumors." (PMID 32373934, 2020). "Moreover, significant down-regulation of RB1 (P=0.005) and up-regulation of CCND1 (P=0.0001) gene was observed in brain tumor sections vs controls." (PMID 32373934, 2020). "Expression levels of RB1 and CCND1 were also analyzed in brain tumor patients." (PMID 32373934, 2020). "Expression levels of selected genes were also assessed at protein level using immunohistochemical analysis (IHC) and signification down-regulation of RB1 (P=0.0001) and up-regulation of CCND1 (P=0.0001) was observed in brain tumor compared with control sections." (PMID 32373934, 2020). "The RB1 mRNA level was negatively correlated with grades (r = −0.252**, P<0.01), however positive correlation was observed for CCND1 mRNA level and grades (r = 0.222*, P<0.05) of brain tumor patients." (PMID 32373934, 2020).
lymphoma (21 papers, 2000 to 2025). A malignant (clonal) proliferation of B- lymphocytes or T- lymphocytes which involves the lymph nodes, bone marrow and/or extranodal sites. "Rb1 protein was previously linked to B cell tolerance in a murine lymphoma model." (PMID 19578517, 2008). "Deletion of Chromosome 13q: Alterations in this region may affect the RB1 gene and other genes that regulate the cell cycle and apoptosis, thereby facilitating lymphoma progression." (PMID 40563566, 2025). "In vitro, G1T38 decreased RB1 (RB) phosphorylation, caused a precise G1 arrest, and inhibited cell proliferation in a variety of CDK4/6-dependent tumorigenic cell lines including breast, melanoma, leukemia, and lymphoma cells." (PMID 28418845, 2017).
soft tissue sarcoma (21 papers, 1989 to 2025). A malignant neoplasm arising from muscle tissue, adipose tissue, blood vessels, fibrous tissue, or other supportive tissues excluding the bones. "A role for Rb1 loss in progression of eRMS and other soft tissue sarcomas has been clearer than for aRMS." (PMID 24274149, 2013). "These CNAs encompass a number of cancer-associated genes, among which a few have already been proposed as candidate genes in the pathogenesis of soft tissue sarcomas, i.e. RB1." (PMID 28331547, 2017). "While RMS is rare as a primary cancer in patients with germline Rb1 haploinsufficiency, RMS is the most common soft tissue sarcoma in a radiation field for these patients." (PMID 24274149, 2013).
viral infection (21 papers, 2013 to 2023). "We can hypothesize that Rb1 might lead to the inhibition of 2009pdm viral infection in α 2–3’ sialic acid containing cells." (PMID 28187149, 2017).
childhood cancer (18 papers, 2013 to 2025). "Looking for second hit mutations in RB1, we applied a custom designed NGS panel (Onconano V2) that included the RB1, BCOR and CREBPP genes (among other 400 commonly mutated genes in pediatric cancer)." (PMID 34479642, 2021).
liposarcoma (17 papers, 2015 to 2026). A usually painless malignant tumor that arises from adipose tissue. "The use of sWGS can reveal that myxoid pleomorphic liposarcomas exhibit complex chromosomal alterations, particularly the loss of 13q14, which encompasses the RB1, RCTB2, DLEU1, and ITM2B genes." (PMID 39473659, 2024). "Similarly, Rb1 expression analysis is valuable in differentiating well-differentiated from dedifferentiated liposarcoma, the latter often exhibiting Rb1 loss and aggressive clinical behavior." (PMID 40870476, 2025). "For instance, the evaluation of CDK 4, MDM2 and RB-1 expression along with Ki67 has shown potential in distinguishing tumors from different prognostic categories, guiding personalized care in liposarcoma management." (PMID 40870476, 2025). "Intriguingly, p16 overexpression was similarly noted in liposarcomas lacking RB1 alterations but harboring ecDNA-based CDK4 amplification." (PMID 39185963, 2025).